INS (insulin)
Diseases named in the same sentence as INS in open-access papers (continued):
Sharing a sentence is not in itself a finding about the gene and the disease.
Obesity (continued). "The first was the diet induced obesity mouse, a hyperinsulinemic, insulin resistant animal, and the second was the multi-low dose streptozotocin/high-fat diet mouse, an insulinopenic, insulin resistant animal." (PMID 24533136, 2014). "While confirming the high prevalence of hypovitaminosis D in severe obesity, current data suggest a possible role for vitamin D in the regulation of glucose tolerance, insulin secretion and lipid metabolism, on which obesity plays per se a dominant effect." (PMID 24618074, 2014). "In fact, obesity leads to sustained activation of IRE1α that impairs insulin signaling through IRE1α/JNK-mediated phosphorylation of IRS-1 that prevents IRS-1 tyrosine phosphorylation by activated IR." (PMID 25398386, 2014). "Coupled to the inflammatory cytokine profiles within fat depots in our stress model, such changes produce a molecular stamp reminiscent of obesity‐like changes in adipocyte function related to insulin sensitivity." (PMID 24819750, 2014). "In this study, we avoided the extreme HFD (60% calorie from fat) feeding, which is known to lead to severe obesity, brain insulin resistance, and spatial memory impairment both in AD mouse model and normal C57BL/6 mouse." (PMID 25152713, 2014). "Future clinical studies are required to determine the role of adipose SFRP5 in the control of obesity-related abnormalities in glucose homeostasis and insulin sensitivity." (PMID 24733068, 2014). "It is generally thought that hyperinsulinemia triggers the expansion of AT in the early phase of obesity and IR of muscle and adipose tissues appears later, suggesting that adipogenesis requires insulin-sensitive fat cells." (PMID 25299671, 2014). "MicroRNAs have now been linked to a variety of biological phenomena, and specifically to insulin secretion, reduced viability and numbers of pancreatic β-cells, glucose metabolism and pathological development of obesity." (PMID 25859286, 2014). "Disruption of the gene encoding IKK and the innate immune system receptor Toll-like receptor (TLR)-4 in mice confers protection from insulin and leptin resistance, and obesity in mouse models." (PMID 24675731, 2014). "Pancreatic beta-cell function and mass are markedly adaptive to compensate for the changes in insulin requirement observed during several situations such as pregnancy, obesity, glucocorticoids excess, or administration." (PMID 24734255, 2014). "We evaluated the effect of macadamia oil supplementation on insulin sensitivity, inflammation, lipid profile, and adipocyte size in high-fat diet (HF) induced obesity in mice." (PMID 25332517, 2014). "We have previously shown that insulin signaling is one of the factors responsible for the development of obesity related hypertension which is later maintained by slowly rising circulating leptin concentrations." (PMID 25520669, 2014). "Although the reality is most probably a mixture of these phenomena, further studies should be carried out to define the role of ROS in the early stages of the development of obesity and its metabolic alterations, such as insulin resistance." (PMID 24562334, 2014). "Adipose tissue hypoxia has recently been proposed as a mechanism for limited insulin signaling in both obesity and obstructive sleep apnea." (PMID 25541690, 2014). "In old adults (25-month-old rats), the obesity in rats fed the HFD was morbid and associated with resistance to insulin, in particular in skeletal muscle as illustrated by the reduced Akt activation." (PMID 25139155, 2014). "In comparison, studies using liposome–encapsulated clodronate to deplete Kupffer cells show that the alleviation of early, within 3 days of HF feeding, liver inflammation can lessen the subsequent development of obesity and insulin insensitivity." (PMID 25170916, 2014).
Obesity (continued). "Expression patterns of this miR varied in response to an acute or chronic dietary stimulus in mice susceptible (C57BL/6J) or resistant (BALB/c) to diet induced obesity, as well as in insulin resistant adipocytes in vitro." (PMID 24675842, 2014). "In summary, aberrant p42/p44 MAPK signalling was the most common problem found in obesity-induced insulin resistant skeletal muscle." (PMID 23468892, 2013). "Increased IGFBP-2 concentrations are protective against the development of obesity and improve insulin sensitivity, while higher IGFBP-1 concentrations are associated with lower insulin levels." (PMID 23516412, 2013). "Overproduced as a central effector of leptin deficiency, NPY is associated with obesity, a typical symptom of T2DM and infertility, and eventually plays a major role on insulin action or secretion regulation in central nervous system (CNS)." (PMID 23671868, 2013). "Much of the phenotyping of the SCD1 KO mouse focused on the fact that SCD1 KO mice were resistant to diet induced obesity and had improved insulin sensitivity." (PMID 23760815, 2013). "In rodent models of obesity that show a failure of insulin to increase muscle perfusion, muscle contraction can still cause capillary recruitment and glucose uptake." (PMID 24772374, 2013). "Improvement of glycemia and insulin sensitivity as well as other co-morbidities is also a therapeutic objective of anti-obesity treatments." (PMID 23922646, 2013). "As we previously showed that the level of HSL expression controls lipolytic rate in human fat cells and is altered in obesity, the association between WAT lipolysis, fat mass, and insulin sensitivity was investigated in mice with HSL haploinsufficiency." (PMID 23431266, 2013). "Fat removal, however, as an independent procedure exacerbated obesity-induced increases in leptin and insulin concentrations." (PMID 23914298, 2013). "β-cell mass flexibly adapts to insulin requirement as shown by the fact that adult β cells expand in response to states of increased demand for insulin such as obesity and pregnancy." (PMID 23593212, 2013). "The pleiotropic effects of inhibition of NLRP3 inflammasome in obesity are evident by improved insulin signaling in adipose tissue, liver, and skeletal muscle and increased insulin secretion in the pancreas." (PMID 23483669, 2013). "High linoleic acid diets promote obesity in both animals and humans and are correlated with increased fasting blood glucose, fasting insulin, and insulin resistance in humans, making this an important area of further research." (PMID 23762050, 2013). "The role of PPAR-β/-δ in the regulation of glucose homeostasis has emerged with the findings that PPAR-β/-δ agonists reduce adiposity and improve glucose tolerance and insulin sensitivity in different mouse models of obesity." (PMID 23781121, 2013). "In murine models, chronic administration of FGF-21 increases insulin-mediated glucose uptake in muscle, but only in diet induced obesity." (PMID 23533568, 2013). "PTP activity has been described to be dynamically enhanced in obesity in insulin-sensitive tissue (adipose tissue, skeletal muscle and liver), with significant reduction after weight loss." (PMID 23889985, 2013). "Animals with reduced BDNF expression due to a conditional knockout in the brain develop hyperphagia, obesity and resistance to insulin." (PMID 23431394, 2013). "Nonetheless, MPV was positively associated with insulin level in polycystic ovary syndrome, which is related to increased insulin levels and the incidence of obesity." (PMID 23311535, 2013). "In obesity, increased production of most adipokines impacts on multiple functions such as appetite and energy balance, modulation of immune responses, insulin sensitivity, angiogenesis, blood pressure, lipid metabolism, and so on." (PMID 24151494, 2013).
Obesity (continued). "This is the first report on insulin sensitivity and β-cell function in preschoolers affected by severe obesity and on longitudinal changes occurring in insulin metabolism at transition from preschool to school age estimated by two serial OGTTs." (PMID 23935878, 2013). "Deletion of STAT3 signaling (STAT3N−/−) from the brain (Nestin-Cre mouse model) resulted in hyperphagic obesity, and high plasma corticosterone, glucose and insulin levels, similar to ob/ob and db/db mice." (PMID 22851226, 2013). "Early in 2001, just 4 years after the discovery of UCP2, it was reported that UCP2 negatively regulated insulin secretion and was a major link between obesity, β-cell dysfunction, and DM2." (PMID 23841103, 2013). "The main findings of the current study implicate, for the first time, attenuation of insulin stimulation of the p42/p44 MAP kinase pathway as an early defect in obesity-induced IR in skeletal muscle." (PMID 23468892, 2013). "Most importantly, our data demonstrate, for the first time, that endogenous CORT is essential for the obesity-induced changes in insulin expression/secretion observed in mice, suggesting that CORT is a key regulatory component of the pancreatic function." (PMID 23469081, 2013). "When fed a high-fat diet (HFD), these mice became more insulin resistant than control mice, suggesting that lymphocytes protect against the deleterious effects of obesity." (PMID 23562076, 2013). "Hyperglycaemia in obesity with the resultant continuous insulin production induces metabolic stress in pancreatic β-cell mitochondria in the islets of Langerhans." (PMID 23983688, 2013). "Serum DPP-4 levels correlate with adipocyte size and adipocytes potentially represent an important source of DPP-4 in obesity, which impairs insulin signaling." (PMID 24188631, 2013). "From our VA status studies, we have shown that VA status affected the obesity development in ZF rats and reduced plasma insulin and TG levels in ZL and ZF rats, suggesting improvement of insulin sensitivity." (PMID 27335827, 2013). "Obesity activates many inflammatory pathways that deregulate physiological responses, which maintain metabolic homeostasis including insulin and leptin sensitivity." (PMID 23594407, 2013). "To further analyze the role of DEP-1 in diet-induced obesity and in insulin signaling we applied DEP-1 antisense oligonucleotides (ASOs)." (PMID 23889985, 2013). "The two lines also diverged for many health indicators, with HCR showing a relative resistance to obesity, higher insulin sensitivity, lower blood pressure, improved lipid parameters, and enhanced longevity." (PMID 24147032, 2013). "More recently, skeletal muscle-specific JNK-1 disruption reported by Sabio and colleagues revealed a potential role of JNK-1 signaling in the control of systemic insulin sensitivity in high fat diet-induced obesity." (PMID 23349837, 2013). "The deregulation of these signaling cascades and their cross-talk with insulin signaling in adipocytes leads to the alterations in energy expenditure and/or feed efficiency and results in obesity and T2DM." (PMID 24191197, 2013). "These aspects of insulin signaling provide mechanistic insight into the clinical evidence for the links between obesity, metabolic syndrome, and airway diseases, setting the stage for novel therapeutic avenues targeting these conditions." (PMID 24204385, 2013). "Since dysfunctional insulin signaling, obesity, elevated inflammation, and cardiac hypertrophy are forerunners to heart failure, this study will also investigate the multifaceted mechanisms by which the HO system preserves cardiac function in ZFs." (PMID 24454978, 2013). "This suggestion is supported by findings that increased ATM is associated with an aggravation of insulin sensitivity, whereas decreased ATM reduces IR caused by high fat diet (HFD)-induced obesity." (PMID 23977220, 2013).
Obesity (continued). "There were higher levels of oxidative stress in the obese diabetics even after control of hyperglycemia by insulin treatment, suggesting the importance of obesity in contributing to oxidative stress." (PMID 23800102, 2013). "Regular physical activity improves insulin function and glucose tolerance in healthy individuals, patients with obesity, insulin resistance, and diabetics." (PMID 23691290, 2013). "The regulation of β-cell mass, (including proliferation, neogenesis, cell size, and apoptosis), is essential for the compensatory response of the endocrine pancreas to increase insulin demand, such as occurs in obesity." (PMID 23579596, 2013). "Adiponectin has been shown to improve a whole-body insulin sensitivity in models of genetic and diet-induced obesity." (PMID 23690769, 2013). "Although islet β-cell secretion increased in the overweight stage, the degree of compensatory increase in insulin secretion reached a plateau, even with increased obesity." (PMID 24137224, 2013). "Obesity and IR are associated to T2DM when the 1Kß-cells are incapable of completely remediating the reduced sensitivity to insulin." (PMID 24892324, 2013). "Moreover, none of the AGPAT6 variants showed association with measures of obesity (waist circumference and BMI), serum lipid concentrations, fasting or 2-h post-glucose load levels of plasma glucose and serum insulin, or estimated indices of insulin secretion or insulin sensitivity." (PMID 24156295, 2013). "It was reported that the fat mass and obesity associated protein, which is the genetic product of FTO, plays a role in the regulation of insulin sensitivity and insulin secretion from pancreatic beta cells." (PMID 23990951, 2013). "Spontaneously hypertensive rats fed with cafeteria diet for 12 weeks showed metabolic changes similar to those of the MS, for example, high plasma levels of glycemia, insulin, triglyceride, leptin, and obesity." (PMID 23691518, 2013). "Data on the relationship between early nutrient intakes, growth patterns and subsequent measures of obesity, insulin sensitivity, cognition and bone mineral density are being further analysed." (PMID 24359608, 2013). "The present study demonstrates that dietary leucine prevents HFD-induced obesity by increasing energy expenditure, locomotor activity and fatty acid oxidation in vivo, consequently leading to decreased adiposity and better insulin sensitivity." (PMID 24086364, 2013). "In genetic and diet-induced obesity, autophagy is markedly downregulated in the liver, leading to reduced hepatic insulin action and increased ER stress, and restoration of autophagy increases insulin sensitivity." (PMID 24167585, 2013). "The anti-obesity effect was accompanied by improvement in plasma glycemia, whole body insulin sensitivity, plasma lipid levels and liver steatosis." (PMID 23922646, 2013). "NLRP3 inflammasome activation in obesity promotes macrophage-mediated T cell activation in adipose tissue and impairs insulin sensitivity creating a chronic pro-inflammatory state that impairs insulin sensitivity." (PMID 23690772, 2013). "In multivariate models, after adjusting for confounders (age, sex, HIV/HAART duration, smoking, obesity, glucose, insulin and lipids), African-Americans and Hispanics had significantly higher HbA1c and 2-hour glucose levels than NHW’s." (PMID 23607267, 2013). "Over-expression or treatment with recombinant FGF21 protects mice from development of obesity and fatty liver and improves insulin sensitivity and comparable metabolic benefits are also observed in rhesus monkeys." (PMID 24205333, 2013). "Those that have been extensively related to obesity, energy homeostasis and insulin signalling, as well as those that can act at an epigenetic level, have been reflected in the table." (PMID 23335998, 2013). "One proposed mechanism linking breastfeeding to obesity development is a “programming” of insulin metabolism and the growth hormone- (GH) insulin-like growth factor- (IGF) axis." (PMID 24236134, 2013).
Obesity (continued). "PPARG activation promotes obesity, despite improved insulin sensitivity in liver and adipose tissue and it is generally overexpressed in steatotic liver." (PMID 24324835, 2013). "FGF21 has been highlighted as a new drug candidate for enhancing insulin sensitivity, inducing lipolysis, and preventing diet-induced obesity in many in vitro and in vivo studies (56, –58)." (PMID 23970879, 2013). "One PTP1B inhibitor, trodusquemine, has been shown to suppress appetite, reduce body weight, and improve plasma insulin and leptin levels in a murine model of diet-induced obesity." (PMID 23092275, 2013). "Overweight and obesity correlate strongly with diminished insulin sensitivity and it is known since long time that most individuals are able to counteract the decreased insulin sensitivity by increasing insulin secretion and beta cell function." (PMID 23762879, 2013). "This HD mouse model expresses full-length human htt with 97Q and develops obesity as well as insulin and leptin resistance." (PMID 24376631, 2013). "The mechanisms previously exposed, through which obesity deregulates the insulin signal, act via activation of Ser/Thr kinases, possibly the same that are involved in the physiological control of insulin signaling." (PMID 24892324, 2013). "To test if treatment with metformin reduces obesity-induced IR, we evaluated the blood glucose levels before and at 5 to 30 min after administration of recombinant human insulin (1 IU/kg), and calculated the constant rate for glucose disappearance (KITT)." (PMID 24204674, 2013). "Omentin-1 levels in blood circulation are inversely related with obesity and suppressed by glucose and insulin." (PMID 23781214, 2013). "The MFe diet resulted in decreased obesity index, insulin level, and nitric oxide serum concentration in the rats, when compared with both the M and C diets." (PMID 23179349, 2013). "Insulin and glucose levels were found associated with AHI and/or ODI and/or nocturnal SaO2 but this was often dependent on obesity." (PMID 23613841, 2013). "We have extensively investigated the determinants of altered insulin stimulated vascular reactivity in insulin resistant patients with obesity by assessing the effects of insulin on vascular responses to vasodilators acting though different mechanisms." (PMID 24177571, 2013). "There is a well known association between obesity and T2DM, but South Asians develop T2DM at lower levels of body mass index (BMI) than Westerners, and are more insulin resistant for any given BMI." (PMID 24148878, 2013). "In skeletal muscle, lipotoxic species interfere with insulin signaling and are thought to be partly responsible for insulin resistance in obesity." (PMID 24381559, 2013). "We correlated the gene expression of FIP1 with obesity markers and with several genes involved in lipid metabolism and insulin signaling." (PMID 24040321, 2013). "In lean mice, a unique population of Tregs has been shown to reside in adipose tissue and their numbers are reduced in insulin resistant models of obesity, where they play a role in the modulation of metabolic parameters." (PMID 23936084, 2013). "Our finding would correspond to an obesity‐like insulin sensitivity, meaning that all our AI patients should be considered at risk for disease and mortality, as if they were several kilograms heavier." (PMID 24146977, 2013). "PTP1B is a negative regulator of the leptin and insulin signaling pathways, so it has emerged as an attractive novel target for the treatment of both type 2 diabetes and obesity." (PMID 23092275, 2013). "Both these studies on Nrf2 activation and its effects in diet-induced obesity converge in the endpoint which is the protection from an obese and insulin resistant phenotype." (PMID 23363332, 2013).